CSF1R (colony stimulating factor 1 receptor)
Diseases named in the same sentence as CSF1R in open-access papers (continued):
Sharing a sentence is not in itself a finding about the gene and the disease.
tumor (continued). "Nevertheless, it will be of interest to follow the response to new drugs, including small molecule kinase inhibitors, currently developed to target CSF-1R in cancer in which the receptor is often over-expressed, either on tumor cells or in the microenvironment." (PMID 24828813, 2014). "Anti-CSF-1R treatment to inhibit tumor growth in vitro and in vivo has been well-documented." (PMID 25071759, 2014). "Our earlier studies demonstrated that anti-CSF1R treatment does not alter the recruitment of monocyte macrophages into inflammatory sites, but does greatly reduce the large numbers of tumour-associated macrophages (TAMs) detected using the MacGreen transgene." (PMID 25137049, 2014). "Therefore, the experimental model adopted here potentially expands what is known on the tumor-supporting, macrophage-independent functions of the CSF-1R in an autocrine setting." (PMID 24722292, 2014). "Finally, we sought to determine if CSF-1R was co-expressed with the stem and progenitor cell markers CD34, CD117, and CD133, since these markers have been associated with tumor initiating cells and as well as drug resistance." (PMID 25295160, 2014). "Importantly, CSF-1R inhibition strongly enhanced tumor control by immunotherapy using tumor-specific CD8 T cells." (PMID 25110953, 2014). "The findings of our study suggest that blocking of CSF-1R in patients may suppress tumor development and invasion by acting on cancer cells itself." (PMID 23561040, 2013). "It needs to remind that other pathways, such as CSF1/CSF1R, may also be involved in macrophage mobilization as demonstrated in other tumor models." (PMID 23940516, 2013). "Inhibition of either EGF receptor or CSF-1R signaling prevents tumour cell motility in vivo." (PMID 22505929, 2012). "In this respect, activation of CSF-1R by its ligand is likely to occur in tumor cells in which CSF-1R and CSF-1 are co-expressed (i.e. autocrine activation), or when CSF-1R is stimulated by CSF-1 released by cancer associated fibroblasts (i.e. paracrine activation)." (PMID 22096574, 2011). "In these fluorescent reporter mice, Csf1r drives a blue fluorescence signal in monocytes and macrophages and CD11c+ conventional dendritic cells express red fluorescence, allowing the visualization of macrophages and dendritic cells that have been recruited to the tumor." (PMID 41050935, 2025). "Additionally, the tumor regression observed with the combination of trastuzumab and CSF1R inhibition suggests that simultaneously targeting cancer cells and modulating the myeloid compartment may enhance macrophage-mediated cytotoxicity." (PMID 40595560, 2025). "Furthermore, tumor heterogeneity and plasticity within the myeloid compartment can lead to compensatory recruitment of other suppressive cells, such as MDSCs or regulatory T cells, reducing the long-term impact of CSF1R blockade." (PMID 40821795, 2025). "The data, primarily from in vitro assays, suggest that CSF-1R signaling in microglia, and possibly brain macrophages, controls not only myeloid proliferation and viability, but also the production of cytokines that modulate the responses of astrocytes and tumor cells in the microenvironment." (PMID 40760255, 2025). "Similarly, the intra-T/peri-T CSF1-R+ cell ratio was significantly lower in the CD68+ macrophage than CD20+ tumor cell compartment (0.7 ± 0.1 vs 1.2 ± 0.3, p = 4e-08) and CSF1-R+ cell count was higher in the macrophage than tumor cell compartment (252.2 ± 61.3 vs 177.6 ± 28.7, p = 8e-06)." (PMID 41415285, 2025). "Moreover, IL-34-dependent CSF-1R activation increased the proliferative index of tumor cells." (PMID 38254773, 2024). "Therefore, targeting the CSF1/CSF1R signaling pathway may represent a promising anti-tumor strategy in the future." (PMID 39416792, 2024). "Notably, regorafenib modulates the VEGFR and CSF1R pathways, suggesting that it might be able to reverse the immunosuppressive gradients of myeloid cells and, thereby, potentiate anti-tumor immune responses." (PMID 38374347, 2024).
tumor (continued). "Therefore, additional studies on different tumor types are required to determine whether CSF-1R is similarly involved in all malignancies and emphasize the significance of this receptor in the TME crosstalk, as well as cancer cell signaling." (PMID 38254773, 2024). "Relatively short term (2–4 weeks) treatment with CSF1R inhibitors results in a significant depletion of Ly6Clow monocytes (equivalent to human non-classical CD16+ monocytes) and M2-polarized tissue and tumour-associated macrophage subpopulations that express CSF1R at higher levels." (PMID 39049445, 2024). "Moreover, we have proposed the notion that anti‐CSF‐1/CSF‐1R targeting M2 macrophages, tumor vaccines or cytokine therapies targeting bystander T cells might be effective for HRP tumors." (PMID 39136172, 2024). "Therefore, Csf1r blockade might be a promising strategy to increase macrophage activity in the context of tumor therapy." (PMID 39603243, 2024). "Finally, we also wanted to understand whether the drugs would influence CSF-1 or CSF-1R expression in tumor cells." (PMID 38303927, 2024). "To investigate whether the upregulation of CSF-1 in EBV-associated tumour cells regulates CCR5 receptor expression on monocytes and migration towards rh-CCL5, we performed chemotaxis experiments in an rh-CCL5 and CSF1 receptor (CSF1R)-inhibited system." (PMID 39267775, 2024). "In addition, CSF1R inhibitors may also be able to be used in combination with chemotherapy, radiotherapy, or other targeted therapies to enhance the tumor cell killing effect." (PMID 39416792, 2024). "Additionally, investigating whether CSF-1R regulation differs from other tumor cell receptors is essential." (PMID 39457693, 2024). "Furthermore, CSF-1R inhibition in CAFs led to a reduction in IL-10 production and an increase in IL-12 production in macrophages and enhanced the cytotoxicity of macrophages against tumor cells, indicating a shift towards an anti-tumor M1-like phenotype." (PMID 39457693, 2024). "In addition, GBM response to CSF-1R inhibition therapy may be related to the dictation of the TME by different tumor subtypes." (PMID 37598273, 2023). "Besides, the CSF1R inhibitor BLZ945 could reprogram TAM from a tumor-promoting toward a tumor-suppressing phenotype, enhancing antigen presentation and T or NK cell activation." (PMID 38008741, 2023). "The findings of these two studies, which employed TAMs depletion therapy in conjunction with OV therapy and immune checkpoint blockades (ICBs), yielded opposite conclusions, which could be attributed to the disparities in the virus type, CSF-1R inhibitors employed, and the tumor type." (PMID 37234776, 2023). "These different outcomes between CSF1R inhibition and MCP abolition can be partially attributed to the inefficacy of CSF1R inhibitor in decreasing tumor-associated macrophage numbers in GBM; therefore, no compensatory recruitment of neutrophils would be present." (PMID 37012245, 2023). "However, patients with unresectable disease, as in the case of infiltrative tumour growth, may benefit from systemic therapy using CSF‐1R inhibitors by avoiding surgery and helping improve functional outcomes." (PMID 38098613, 2023). "Furthermore, blockade of CSF1R combined with STAT5 signaling inhibitor could sustain tumor control and rectify adaptive resistance to CSF1R inhibition." (PMID 37731483, 2023). "To assess the diffusion of CSF1R/CCR2/TGF-β Ab from the vasculature and its ability to reach the tumor spheroids, we perfused a device with fluorescently labeled CSF1R/CCR2/TGF-β Ab and found that the drug could penetrate the spheroid compartment within 2 hours after perfusion." (PMID 38076998, 2023). "Indeed, blockade of M-CSF/CSF1R leads to macrophage reprogramming and loss of TAM in the tumor, while blockade of macrophage PI3Kγ in an animal model of pancreatic ductal adenocarcinoma reprograms TAM for immunostimulation and inhibition of tumor metastasis." (PMID 36380627, 2023).
tumor (continued). "Furthermore, the study showed that the suppression of macrophage by CSF-1R inhibitor could inhibit the proliferation and angiogenesis of tumor cells." (PMID 37335645, 2023). "CSF1R blockade also trended to decrease the frequency of intratumoral tetramer+ T cells (P = 0.077), suggesting TAMs may recruit and/or retain tumor-specific T cells." (PMID 35393950, 2022). "Therefore, the up-regulation of Csf1r as a consequence of Mir34a inactivation in intestinal adenomas is an important mediator of tumor/stroma interactions, which may promote tumor initiation and progression." (PMID 36147476, 2022). "Furthermore, inhibiting the colony-stimulating factor-1 receptor (CSF1R) in TAMs might significantly reduce tumor-initiating cells (TICs), hence relieving immunosuppression and overcoming TIC-mediated chemotherapeutic resistance." (PMID 39280892, 2022). "Therefore, we reasoned that CSF-1R mainly exerts pro-tumor functions in the TME." (PMID 35444953, 2022). "Treatment targeting the receptor or its ligand, CSF-1R/CSF-1, has been found to improve T cell responses; further, combining CSF-1R inhibition with checkpoint blockades or adoptive T cell transfer therapy resulted in an improved anti-tumor T cell activity and tumor regression." (PMID 35628647, 2022). "In addition, absence of CSF1R+ expression by macrophages was associated with reduced myeloid-derived suppressor cells (MDSCs), increased tumor CD8+ cell infiltration, and enhanced CD8+ cell activation in tumors." (PMID 35315360, 2022). "In MM, a recent preclinical study has demonstrated a significant reduction in tumor burden following treatment with the anti-CSF1R antibody, suggesting that targeting macrophages, via CSF1R, in combination with standard therapies, may be a promising therapeutic strategy in MM." (PMID 35954459, 2022). "Importantly, the genetic inactivation of PI3Kδ in Treg cells mediated a sensitization of tumor cells to the depletion of CSF1R+ TAMs and combinatorial approaches that simultaneously inhibited CSF1R and PI3Kδ substantially synergized to impede tumor progression." (PMID 36230505, 2022). "Previous studies support that blocking CSF1R could delay tumor growth via TAM reduction." (PMID 36209194, 2022). "Antibodies designed to broadly deplete TAMs, such as CCL2/CCR2 and CSF-1/CSF1-R neutralising mAbs have performed poorly in the clinic as single agents, characterised by both a lack of effect on specific pro-tumoural subsets and collateral inhibition of anti-tumour TAM activity." (PMID 35020853, 2022). "In addition, our expression analyses showed that, among potential Mir34a targets, genes associated with the induction of STAT3, JUN and SRF expression signatures are presumably involved in the opposing regulation of intestinal homeostasis and tumor formation by Mir34a and Csf1r signaling." (PMID 36147476, 2022). "Taken together, these results suggest that tumor-induced mice (post-tumor model) shared characteristics of Lal–/– mice (pre-tumor model) by increasing CD11c+ cells with immunosuppressive activity in the blood, in which PD-L1, CSF1R, and glucose metabolic enzyme were upregulated." (PMID 35917184, 2022). "Agonist CD40 antibodies have induced anti-tumor effects in several tumor models and the effect has been more pronounced when used in combination with other treatments (immune checkpoint inhibition, chemotherapy, and colony-stimulating factor 1 receptor inhibition)." (PMID 33804039, 2021). "The physiological distribution and tumor uptake of CSF1R mAbs are unknown." (PMID 34976826, 2021). "As anti-CSF-1R only enhanced the efficacy of combined IT against TC-1/A9 tumors, we next investigated whether a similar tumor growth inhibition could be achieved in this tumor type, using the same dose number of either ODN1826 or anti-CSF-1R, applied separately into the immunized mice." (PMID 34205330, 2021).
tumor (continued). "By analyzing the clinical outcome and tumor immune microenvironment from 109 stage III or high-risk stage II CRC patients, this study identified several important findings: (i) CRC patients with CSF1R c.1085 genotype A_A had a worse overall survival than patients with CSF1R genotype A_G." (PMID 34830445, 2021). "In preclinical models, blockade of CSF-1/CSF-1R signaling inhibited recruitment of bone marrow myeloid cells to the tumor during chemotherapy and induced type I interferon response, thereby reversing chemoresistance and sensitizing tumor cells to chemotherapy 1-3." (PMID 33537102, 2021). "Moreover, anti-CSF1R failed to prevent lethal weight loss or transaminitis in either tumor-bearing or non–tumor-bearing mice." (PMID 34101617, 2021). "A case analysis indicated that despite TAS-115 treatment discontinuation after 1 week, PET-CT imaging at 6 weeks confirmed signal attenuation of bone metabolic markers, which we hypothesise may have been due to improved antitumour immune defences in the tumour microenvironment by CSF-1R inhibition." (PMID 34117970, 2021). "Noninvasive imaging of myeloid cells that illuminates the effects of CSF-1/CSF-1R blockade on the bone marrow, spleen, and tumor may improve understanding of the engagement of CSF-1/CSF-1R pathway inhibitors in patients, thereby facilitating the development of optimal combination strategies." (PMID 33537102, 2021). "Firstly, macrophage markers IL6, CSF1R, CXCL12 were weak-to-strong positively associated with NEFM expression, which could reveal a potential role of NEFM transcriptional expression in regulating polarization of tumor-associated macrophage (TAM)." (PMID 34001208, 2021). "Our biomarker study demonstrates that CSF-1R expression on tumor-associated macrophages does not provide prognostic value; however, it is likely that in vivo CSF-1R expression on both the carcinoma cells and host macrophages contributes to the pharmacologic effects of inhibitors." (PMID 34830923, 2021). "Thus, like the case for CSF1R+ macrophages, it is possible that MMPs may contribute to toxicity in the context of a tumor-bearing host." (PMID 34101617, 2021). "This is the first report of local LN macrophage depletion using a s.c. injection of CSF-1R depleting antibody, but s.c. administration is a recently validated strategy for the locoregional enrichment of blocking antibodies such as checkpoint antibodies in the sentinel LNs for tumor control." (PMID 34630389, 2021). "However, even in tumor-bearing mice, anti-CSF1R treatment failed to mitigate treatment-induced weight loss or transaminitis triggered by CD40 chemoimmunotherapy." (PMID 34101617, 2021). "However, because AML can arise from macrophage-lineage precursor cells, it can be challenging to determine the origin of supportive CSF1R-expressing cells, and to know whether they are infiltrating monocytes/macrophages or tumor derived." (PMID 33842370, 2021). "Importantly, CTLA-4 blockade monotherapy upregulated the expression of CSF-1R in tumor-infiltrating MDSCs and inhibited T cell proliferation, whereas anti-CSF-1R and CTLA-4 blockade combined treatment induced antitumor T-cell responses and tumor regression in multiple tumor models." (PMID 32942545, 2020). "A high density of CSF-1R in peritumoral liver tissue, but not in tumor tissue, was associated with poor survival and a high incidence of metastasis after resection of the primary tumor." (PMID 32760707, 2020). "Treatments targeting the receptor or its ligand CSF-1R/CSF-1 has been found to improve T-cell responses and combining CSF-1R inhibition with checkpoint blockades or adoptive T-cell transfer therapy resulted in improved anti-tumour T-cell activity and tumour regression." (PMID 32121014, 2020). "Thus, an immune cell composition of CD4+CD68+CSF1R+ could exert strong anti-tumor effects with great cooperativity between these immune factors." (PMID 32850346, 2020).
tumor (continued). "Future studies should examine whether CSF1/CSF1R acts synergistically with CD4+ Th1 cells to activate anti-tumor CD68+ macrophages, or adaptive CSF1 secretion upon exposure to CD4+ T cell-derived cytokines act detrimentally to recruit M2-like TAMs and consequently hamper antitumor immune responses." (PMID 32850346, 2020). "Furthermore, tumor regression could be strengthened by blocking CSF-1R with a combination of PD-1 and/or CTLA-4 antibodies." (PMID 32359357, 2020). "The authors also indicated that CSF1/CSF1R blockade might reduce PD-L1 expression in tumor cells." (PMID 31521128, 2019). "Anti-CD40 was combined with anti-CSF-1R to create a pro-inflammatory environment eliciting T-cell responses before depletion of TAMs or with chemotherapies such as imatinib (tyrosine kinase inhibitor) with strong tumor regression in a gastrointestinal tumor mouse model." (PMID 31547627, 2019). "PLX3397, a competitive inhibitor for CSF-1R, could delayed tumor growth murine xenograft models." (PMID 31572568, 2019). "However, targeting CSF-1/CSF1-R axis could also lead to compensatory effects, which translate to enhanced tumour progression." (PMID 31331034, 2019). "Colony-stimulating factor 1 receptor (CSF1R) tyrosine kinase inhibition reduces murine PCa TAMs 15-fold, lowers expression of the Vegfa, Mmp9, and Arg1 M2 mRNAs in the remaining TAMs, and delays tumor progression, with similar findings in immune-deficient mice inoculated with a human PCa line." (PMID 29324844, 2018). "However, when targeted by CSF1R inhibitors, the TAMs could switch to an anti-tumorigenic M1 phenotype and promote tumor cell death." (PMID 30619286, 2018). "However, resistance to CSF1R-targeted therapy might arise via tumor secretion of alternative M2-polarizing cytokines, such as IL-4, as seen in a glioma model." (PMID 29324844, 2018). "Moreover, CSF-1R blockade using monoclonal antibodies or small molecule inhibitors not only leads to a reduced attraction of monocytes to the tumor, but also to the preferential differentiation of monocytes toward M1 TAMs, resulting in a higher intratumoral M1/M2 ratio in mice." (PMID 30349530, 2018). "In a mouse model of BrC, Swierczak and colleagues found that blocking the CSF-1 (M-CSF)/CSF-1R interaction to prevent recruitment of circulating monocytes and M2 polarization increased the serum levels of G-CSF, leading to increased neutrophils in the primary tumor, and increased lung metastasis." (PMID 28337194, 2017). "Moreover, compared with the normal kidney tissues, the stromal populations (from FCGR3A to CSF1R) were notably increased, indicating that stromal populations may regulate tumor progression." (PMID 28846080, 2017). "Moreover, in pancreatic tumours, targeting TAMs by inhibiting either the myeloid cell receptors colony-stimulating factor-1 receptor (CSF1R) or chemokine (C-C motif) receptor 2 (CCR2) decreased the number of tumour-initiating cells (TIC) and inhibited metastasis." (PMID 29065107, 2017). "Furthermore, recent preclinical studies as well as a clinical trial in diffuse‐type giant cell tumor patients provided evidence that the functional blockade of CSF1R impairs tumor‐promoting functions either by decreasing total TAM number or, alternatively, by reeducating TAMs." (PMID 26666269, 2016). "Overall, recent reports indicating that CSF1R blockade may be useful for enhancing tumor control through the suppression of tumor immunity suggest that strategies pursuing the inhibition of CSF1R may operate through multiple mechanisms for improving clinical outcomes in cancer patients." (PMID 27516055, 2016). "When tumor cells from Ki20227-treated animals were stimulated with TAMs from untreated non-VE old mice they no longer increase sphere formation in respond, indicating that macrophage depletion by inhibition of CSF-1R prevents the development of the TAM-responsive TICs after surgery." (PMID 25762633, 2015).